BRCA1P1 (BRCA1 pseudogene 1)
Synonyms: LBRCA1; PsiBRCA1; pseudo-BRCA1
Gene: Unprocessed pseudogene on chromosome 17 (43,168,170 to 43,168,249, reverse strand). Ensembl gene ENSG00000267595.
Diseases named in the same sentence as BRCA1P1 in open-access papers:
BRCA1P1 is named in the same sentence as 5 diseases in open-access papers, as found by Europe PMC text mining. Sharing a sentence is not in itself a finding about the gene and the disease. The quoted sentences say what the papers report.
breast carcinoma (2 papers, 2021 to 2026). "Finally, in a humanized mouse model of breast cancer, BRCA1P1 loss stimulates antiviral gene expression and increases T cell infiltration into tumors." (PMID 42081726, 2026). "We identified the BRCA1 pseudogene (BRCA1P1), a fusion pseudogene derived from the BRCA1 tumor suppressor and RPLP1 ribosomal protein genes, as an immunoregulatory RNA in breast cancer." (PMID 42081726, 2026).
breast tumor (1 paper, 2026). "Furthermore, intratumoral expression of BRCA1P1 is elevated in tumor cells, compared to normal breast tissue, and its depletion significantly inhibits the growth of both primary and metastatic breast tumor organoids." (PMID 42081726, 2026).
cancer (2 papers, 2021 to 2026). A tumor composed of atypical neoplastic, often pleomorphic cells that invade other tissues. "This antiviral response also enhances macrophage-mediated phagocytosis of BRCA1P1-deficient cancer cells." (PMID 42081726, 2026). "Loss of BRCA1P1 induces antiviral gene expression, promotes apoptosis, and increases sensitivity to chemotherapy in various cancer cells, without inducing apoptosis in nonmalignant cells." (PMID 42081726, 2026). "Interestingly, BRCA1P1 inhibition elicits antitumor effects in multiple cancer cell types and preclinical tumor models through an antiviral defense mechanism." (PMID 42081726, 2026). "However, these deletions, which usually contain BRCA1, NBR2, BRCA1P1, and NBR1 genes, are not restricted to the NBR2 gene, and further studies are needed to confirm whether a specific deletion of the NBR2 gene determines cancer susceptibility." (PMID 34926299, 2021).
BRCA1P1 also shares sentences with these, for which no sentence is quoted: tumor (2 papers); ovarian tumors (1).